MTOR (mechanistic target of rapamycin kinase)
Diseases named in the same sentence as MTOR in open-access papers (continued):
Sharing a sentence is not in itself a finding about the gene and the disease.
cancer (continued). "Hyperactivation of the PI3K/AKT/mTOR network occurs in almost all malignant tumors and is essential for cell motility, growth, survival, and metabolism in patients with cancer." (PMID 40537911, 2025). "In another work, inhibition of mTOR signaling in multiple cancer cell lines led to the stabilization of PD-L1 via inhibition of β-TRCP." (PMID 39851497, 2025). "Key pathways include NF-κB, MAPK, PI3K/AKT/mTOR, and KP/AhR, which regulate cancer cell proliferation, angiogenesis, immunosuppression, and inflammatory responses." (PMID 40075568, 2025). "The PI3K/AKT/mTOR axis is among the most dysregulated pathways in cancers, prompting studies to reveal new aspects of this pathway in tumorigenesis." (PMID 40740483, 2025). "The suppression of mTOR during fasting is therefore a key mechanism through which fasting exerts anti-cancer effects." (PMID 39940361, 2025). "Our study shows the key role of PI3K/AKT/mTOR in regulating SERPINB6's maintenance of cancer cell migration and proliferation." (PMID 40665565, 2025). "Mechanistically, HKDC1 enhances glycolytic flux through modulation of the AMPK/mTOR signaling pathway, thereby supporting cancer cell metabolism and growth." (PMID 41049000, 2025). "It has been proven that this compound blocks the PI3K/Akt/mTOR pathway, which is overactivated in many types of cancer." (PMID 40430886, 2025). "Along with this, the mTOR signaling pathway, which regulates cellular metabolism and growth, is frequently hyperactivated in various cancers." (PMID 40051496, 2025). "The involvement of FOXK1 in activating the AKT/mTOR signaling pathway further supports its implication in the malignancy of various cancers." (PMID 39981141, 2025). "The dysregulation of this PI3K/AKT/mTOR pathway is involved in multiple cancer developments, including BC." (PMID 40964147, 2025). "Numerous studies have indicated that the PI3K/AKT/mTOR signaling pathway plays a crucial role in the onset and progression of various cancers." (PMID 40328748, 2025). "This dual enzymatic inhibition disrupts PI3K/Akt/mTOR signaling and counteracts the Warburg effect, two hallmarks of cancer cell survival." (PMID 40299634, 2025). "In many human cancers, mTOR signaling is upregulated, as it is in AD patients, and this upregulation leads to a decrease in autophagy." (PMID 40357169, 2025). "Abnormal mTOR activation happens frequently in cancer and is an essential phase in the advancement of the disease." (PMID 40487371, 2025). "The findings suggest that the regulation of RNA processing by mTOR is crucial for understanding diseases such as cancer and metabolic disorders." (PMID 40804480, 2025). "This study focuses on developing new drug-like molecules that can block a key protein called mTOR, which plays a crucial role in cancer cell growth and survival." (PMID 40075606, 2025). "A promising research direction involves targeting the PI3K/AKT/mTOR pathway, which has been linked to MAPK inhibitor resistance across various cancer types, including CRC." (PMID 41255582, 2025). "EA has also been reported to modulate other key metabolic pathways, including AMPK/mTOR, which are crucial in cancer cell survival and proliferation." (PMID 41229448, 2025). "The results from the same team show that IL-11 activates mTOR signaling and identify that the IL-11/mTOR axis acts as a signaling commonality in stromal, epithelial, and cancer cells." (PMID 40092733, 2025). "The PI3K/AKT/mTOR signal transduction pathway is constitutively active in many cancers, including breast, lung, and colon cancers." (PMID 40563640, 2025). "Glycolytic metabolites exert dual regulatory effects on the activation of the PI3K/AKT/mTOR pathway in cancer cells." (PMID 41168198, 2025). "mTOR inhibitors like AZD-8055 target a critical pathway involved in cancer cell growth and survival." (PMID 40301300, 2025).
cancer (continued). "RSAD2, an interferon-inducible gene, is upregulated by the PI3K/AKT/mTOR pathway and serves as a key factor for metabolic reprogramming to promote stem-like properties of cancer stem cells and tumor proliferation." (PMID 41439936, 2025). "For instance, quercetin, resveratrol, and curcumin exhibited cancer therapeutic effects by modulating genes related to the PI3K/AKT/mTOR pathway." (PMID 41180483, 2025). "The mTOR pathway is often hyperactivated in cancer cells, making the inhibition of mTOR signaling a promising and effective approach for molecular targeted therapy in human cancers." (PMID 40697520, 2025). "Among the signaling pathways involved in cancer, two pathways are frequently activated or mutated in cancer, in particular, the PI3K/AKT/mTOR signal transduction pathway and the RAS/MAPK pathway." (PMID 41471069, 2025). "Fatostatin, Betulin, and Xanthohumol have been shown to suppress cancer progression not only via the SCAP-SREBP pathway but also through inhibition of mTOR, MAPK, and Notch signaling." (PMID 40308757, 2025). "While long noncoding RNAs have been investigated as regulators of mTOR signaling in cancers, the role of circRNAs remains largely unclear." (PMID 40263288, 2025). "The mTOR pathway plays a vital role in normal physiological processes but is also dysregulated in various malignant tumors and promotes tumor progression through various mechanisms." (PMID 40140647, 2025). "In contrast, analysis of hypomethylated genes in tumors from European ancestry revealed enrichment in proteoglycans in cancer, the mTOR signaling pathway, cellular senescence, oocyte meiosis, and the AMPK signaling pathway." (PMID 40045917, 2025). "Significant upregulation of the PI3K/AKT/mTOR signaling cascade has been observed in many types of cancers." (PMID 40427108, 2025). "This pathway likely contributes to cancer cell survival during the PI3K/AKT/mTOR/p-PKM2(Y105)-driven Warburg effect by promoting a sustained glycolytic rate that supports rapid cell proliferation." (PMID 41009024, 2025). "Inhibitors targeting the PI3K/mTOR pathway have been shown to combat tumors by triggering apoptosis or autophagy in cancer cells." (PMID 41471338, 2025). "l‐leucine activates Akt/mTOR signalling and reduces E3 ubiquitin ligase expression, but excessive intake can increase plasma ammonia levels and promote cancer growth." (PMID 40810552, 2025). "The significant enrichment of five cancer-related hallmark pathways were revealed in the high-risk group through GSEA, including DNA repair, E2F targets, MYC targets V1, PI3K/AKT/MTOR signaling, and reactive oxygen species pathway (FDR < 0.05)." (PMID 41200185, 2025). "The mTOR pathway is a key regulator of cell growth and proliferation, and its activation by amino acids such as leucine supports cancer cell survival and resistance to therapy." (PMID 40923294, 2025). "The findings imply that the deregulation of the mTOR pathway in cancer provides a compelling basis for therapeutic treatments." (PMID 40717210, 2025). "Cancer cells often show excessive activity of pro-survival signaling pathways such as PI3K/Akt/mTOR." (PMID 40430886, 2025). "As a downstream protein of PI3K/Akt, the mammalian target of rapamycin (mTOR) is tightly correlated with tumorigenicity of cancer stem cells (CSCs)." (PMID 41145413, 2025). "Under stress conditions (nutrient deprivation, chemotherapy), inhibition of PI3K/Akt/mTOR can activate autophagy, promoting cancer cell survival by recycling intracellular components." (PMID 39996741, 2025). "Various signaling pathways, like PI3K/AKT/mTOR and EGF/RAS/RAF/MEK/ERK, are pivotal in oncogenesis, associated with cancer progression and drug resistance in different types of human cancer." (PMID 40806663, 2025).
cancer (continued). "This work highlights AMPK as a potential therapeutic target in EHE and supports the growing body of evidence favoring mTOR inhibitors as promising treatments for this rare cancer." (PMID 40940986, 2025). "Everolimus is used as an mTOR inhibitor in the suppression of cancer development, however, its clinical application is limited because of side effects." (PMID 40374533, 2025). "This suggests that, under conditions of low nutrient availability, FA− cancer cells become reliant on mTOR-mediated translation." (PMID 40805278, 2025). "Excessive activation of the PI3K/AKT/mTOR signaling pathway stimulates uncontrolled cell proliferation and easily induces cancer." (PMID 40002810, 2025). "Preclinical studies with mouse or human cancer cells in vitro and in vivo have demonstrated anti‐tumoral efficacy of combining mTOR inhibitors with ICI such as PD‐1/PD‐L1 inhibitors and others." (PMID 39258533, 2025). "After analyzing rates of concurrent MAPK and mTOR pathway mutations in patients with HER2-amplified CRC, it was found that the rates of these mutations varied based on the location of the cancer." (PMID 40742050, 2025). "The crosstalk between Hippo/YAP and mTOR signaling pathways represents a metabolic vulnerability in cancers, highlighting opportunities for dual targeting of transcriptional and nutrient-sensing pathways to disrupt tumor progression." (PMID 40673277, 2025). "As an inhibitor of the mTOR pathway, rapamycin is widely used to promote autophagy in cancers and neurodegenerative diseases." (PMID 40135197, 2025). "Based on KEGG analysis, we identified the involvement of the PI3K, AKT, and mTOR signaling pathways in regulating EAAs within the central carbon metabolic network of cancer cells." (PMID 41568043, 2025). "The mammalian target of rapamycin (mTOR) kinase is a master regulator of protein synthesis that couples nutrient sensing to cell growth and cancer." (PMID 39941741, 2025). "Alterations in the PI3K/AKT/mTOR pathway: The PI3K/AKT/mTOR pathway plays a crucial role in cancer development and progression, including gynecological malignancies." (PMID 40647429, 2025). "Over-activated mTOR signaling will directly or indirectly induce cancer, metabolism, and aging-related diseases." (PMID 39942843, 2025). "Paradoxically, co-expression of TRIM21 interrupted the Flag-hSPAR-mediated inhibitory effects on mTOR signaling and cancer proliferation, suggesting the indispensable role of TRIM21 in hSPAR’s anti-tumor functions." (PMID 39875724, 2025). "These complex signaling networks and the multifaceted effects of mTOR inhibitors have the potential to yield new and effective strategies for cancer treatment." (PMID 41300706, 2025). "mTOR inhibitors significantly reduce aging and extend lifespan in mice, and are currently used in clinical practice to treat various cancers, transplant rejection, graft restenosis, and tuberous sclerosis complex." (PMID 40496859, 2025). "In malignant tumors, the balance between upstream activators and downstream effectors of mTOR is disrupted, further confirming the critical role of mTOR in cancer development." (PMID 40575656, 2025). "The interplay between these mutations exacerbates oncogenic signaling pathways, particularly the PI3K/AKT/mTOR pathway, further promoting cancer cell proliferation and survival." (PMID 39858102, 2025). "PI3K/Akt/mTOR signaling is one of the important signaling pathways regulating cellular function, and PI3K/Akt/mTOR hyperactivation is seen in most solid tumors and is one of the most common dysregulated signals found in cancer patients." (PMID 40535810, 2025). "One of the pathways that are most frequently activated in a variety of cancer types is the PI3K/AKT/mTOR pathway." (PMID 39886047, 2025). "The regulation of the mammalian target of rapamycin (mTOR) protein by cancer cells can lead to uncontrol of cancer cell growth and cancer therapy resistance." (PMID 40287470, 2025).
cancer (continued). "This combination also potentially inhibits cancer cells by down-regulating the AKT/mTOR signaling pathway, activating the antioxidant response of NRF2 and affecting the intracellular autophagy mechanism in lung cancer (A549) cells [1068]." (PMID 40490812, 2025). "Similar to CR, rapamycin’s mTOR inhibition promotes autophagy and reduces cellular proliferation rates, thereby limiting the conditions that favor cancer growth." (PMID 39940361, 2025). "Dysregulation of mTOR exists in several diseases, including cancer, because its overactivation can promote tumor growth and survival." (PMID 39941728, 2025). "In the tumor context, AMPK plays a dual role: it can act as a tumor suppressor by downregulating the mechanistic target of rapamycin kinase (mTOR), thereby inhibiting cell growth, but it can also promote cancer cell survival in unfavorable environments." (PMID 40227837, 2025). "Given the critical role of the PI3K/Akt/mTOR pathway in cancer, numerous therapeutic strategies have been devised to target various components of this pathway." (PMID 40080721, 2025). "It was later discovered that dysregulation of this mTOR pathway is common in many cancers, contributing to abnormal cell growth, metabolism, and resistance to cell death." (PMID 40652143, 2025). "Later studies led to identifying and cloning the mammalian target of rapamycin, mTOR (mammalian Target of Rapamycin), which, along with its subsequent downstream targets, have emerged as candidates for cancer therapies." (PMID 40243440, 2025). "mTOR, a serine/threonine kinase frequently deregulated in cancer, is involved in various cellular processes and is therapeutically targeted in cancer treatment." (PMID 40064787, 2025). "The mammalian target of rapamycin (mTOR) pathway is central to autophagy regulation, with its inhibition leading to increased autophagic flux and enhanced cancer cell survival." (PMID 40722763, 2025). "Dysregulation of the PI3K/AKT/mTOR axis has been observed in human cancers, increasing proliferation and metastasis." (PMID 40740483, 2025). "The activation of the PI3K/AKT/mTOR pathway, which controls important cellular functions, encourages cancer by promoting unchecked angiogenesis, invasion, and proliferation." (PMID 40973691, 2025). "Activated Akt phosphorylates downstream targets, such as the mammalian target of rapamycin (mTOR) and glycogen synthase kinase-3β, promoting cancer cell proliferation, immune evasion, and metastasis." (PMID 40563359, 2025). "Analysis of cell lines in the DEPMAP showed that high levels (>median) of the TXNRD1 gene and increased levels of mTOR p-Ser2448 protein are statistically significantly correlated to resistance against CDDP in tested cancer cell lines." (PMID 39859517, 2025). "Through these associations, Gαi proteins play a significant role in activating the Akt-mTOR signaling pathway, underscoring their importance as oncogenic drivers and their potential as targets for cancer therapies." (PMID 40537499, 2025). "TAS-115, as a multi-targeted kinase inhibitor, disrupts pro-survival signaling by blocking c-MET/HGF and VEGFR2 pathways, thereby attenuating downstream PI3K/Akt/mTOR activation and diminishing the ability of cancer cells to withstand stress." (PMID 41289612, 2025). "Although inhibition of the PI3K/AKT/mTOR axis can reduce tumorigenesis and apoptosis, it can also mediate protective autophagy, thereby enhancing cancer progression." (PMID 40740483, 2025). "In gastric cancer cells, it impedes the Akt/mTOR signaling pathway; blocking this pathway curtails cancer cell proliferation while inducing apoptosis and cytoprotective autophagy, thus impeding cancer cell growth through multiple mechanistic routes." (PMID 40363681, 2025). "It induces autophagy through AMPK/mTOR signaling, hence enhancing its anti-cancer properties, especially under hypoxic conditions in esophageal cancers." (PMID 40004215, 2025).
cancer (continued). "Curcumin exerts notable anti-apoptotic effects in various malignant tumors by modulating the PI3K/Akt/mTOR signaling pathway." (PMID 40575656, 2025). "Consistent with this, we observed positive correlations between p62 and mTORC1 signaling in 21 cancers, in line with prior reports that p62 activates mTORC1 via interaction with Raptor and regulation of mTOR ubiquitination." (PMID 41291343, 2025). "Overall, the PI3K/AKT/mTOR pathway represents a critical signaling cascade frequently dysregulated in cancers, making this signaling a promising target for therapeutic intervention." (PMID 40427108, 2025). "Although mTOR inhibitors alone have limited anticancer effects, mTOR inhibitors have synergistic cancer activity with anti‐PD‐1 antibodies or other treatments (such as metformin)." (PMID 41346571, 2025). "Using genomic and proteomic data in DEPMAP database, we found that the expression of TXNRD1 and STAT3 genes and mTOR pS2448 protein were higher in CDDP resistance cancer cells compared to sensitive cancer cells to CDDP." (PMID 39859517, 2025). "mTOR drives protein synthesis, metabolic adaptation, and angiogenesis, processes that are often hyperactivated in cancers." (PMID 40727094, 2025). "In contrast, oncology—a field frequently impacted by dysregulation of the mTOR pathway in various cancers —has witnessed numerous successful trials employing viral vectors." (PMID 40358185, 2025). "Inhibiting cell proliferation, survival, angiogenesis, metastasis, and migration, kaempferol has been demonstrated to modify several molecular mechanisms and pathways, including the PI3/Akt, mTOR, and Erk/MAPK pathways implicated in the advancement of cancer." (PMID 40868987, 2025). "While much attention has been given to the fact that PIK3CA (encoding PI3Kα) is a frequently mutated gene in cancer, it is striking that mutations in the broader PI3K/AKT/mTOR pathway significantly outweigh PIK3CA mutations in solid tumours." (PMID 40360883, 2025). "The Cav cytotoxic effect depends on its elevated uptake by cancer cells, specific dysregulation of the mTOR/eiF2α signaling, Cav misincorporation into nascent proteins instead of Arg, exacerbation of ER stress, and progression of apoptosis." (PMID 41003496, 2025). "Metformin (MTF), which is an antihyperglycemic agent and first‐line treatment for diabetes, has been found to inhibit mTOR pathway in several cancer types." (PMID 40385549, 2025). "The results indicated that SM-3 treated spheroid cells exhibited a greater reduction in mTOR and pAkt expression compared to Res-treated spheroids across all cancer cell lines (A549, H292, and H460)." (PMID 40287470, 2025). "This study was aimed at uncovering the anti-tumor mechanisms of YYN-37 across different cellular contexts, thereby offering foundational insights and innovative perspectives for the development of anti-cancer therapeutics targeting the PI3K/mTOR pathway." (PMID 41471338, 2025). "PI3K/AKT/mTOR is an important intracellular signaling pathway involved in regulating the occurrence and development of cancer, including cell metabolism, cell proliferation, cell apoptosis, and immune monitoring of the tumor microenvironment 43-45." (PMID 40083706, 2025). "SCFAs, derived from resistant starch as prebiotics, can induce autophagy in cancer cells by downregulating mTOR signaling." (PMID 40299687, 2025). "This leads to activation of the PI3K/AKT/mTOR signaling pathway, which plays a crucial role in cell growth and survival and ultimately contributes to cancer progression." (PMID 41141380, 2025).